IL6 (interleukin 6)
Diseases named in the same sentence as IL6 in open-access papers (continued):
Sharing a sentence is not in itself a finding about the gene and the disease.
Insulin resistance (continued). "TNF-α and IL-6 are pro-inflammatory cytokines secreted from the peri-visceral fat; their effect is linked to insulin resistance, atherosclerosis, and endothelial dysfunction." (PMID 39204094, 2024). "Insulin resistance has been linked to the presence of several pro-inflammatory cytokines, including IL-6, as well as SOCS, ER stress, and the inhibitor of nuclear factor kappa-B kinase subunit beta (IKKB) and c-Jun N-terminal kinase (JNK) signaling pathways." (PMID 38317257, 2024). "Elevated plasma concentrations of inflammatory mediators such as tumor necrosis factor α and interleukin-6 are linked to insulin resistance and T2DM." (PMID 39062034, 2024). "NODAT exhibits a strong connection with visceral obesity, leading to the generation of inflammatory cytokines such as interleukin-6 and tumor necrosis factor-α, along with reduced levels of adiponectin associated with insulin resistance." (PMID 38610694, 2024). "IL-6 can disrupt insulin signaling and activity, leading to the development of insulin resistance, which is one of the key mechanisms underlying hypertension." (PMID 38515520, 2024). "For instance, elevated levels of IL6 have been associated with insulin resistance and the progression of diabetic complications like nephropathy and retinopathy." (PMID 38270651, 2024). "Proinflammatory cytokines produced by immune cells and secreted by the adipose tissue, such as TNF-α, IL-4, and IL-6, stimulate obesity-associated diseases, including insulin resistance, dyslipidemia, and cardiovascular diseases." (PMID 39204167, 2024). "Chronic low-grade inflammation, mediated by pro-inflammatory cytokines such as TNF-α and IL-6, has been implicated in the pathogenesis of insulin resistance." (PMID 39211341, 2024). "In contrast, a study investigating specific genetic variations in the IL6 promoter, including − 174 G/C and − 572 G/C polymorphisms, found associations with insulin resistance, dyslipidemia, and increased serum insulin release." (PMID 38388670, 2024). "High levels of IL-6 are considered risk factors for metabolic syndrome as they cause lipid and vascular changes that accompany insulin resistance." (PMID 38734032, 2024). "Increased TNF-α levels have also been demonstrated to cause insulin resistance by affecting insulin signaling and glucose absorption in vivo, similarly to IL-6." (PMID 38390960, 2024). "Long-term exposure to elevated levels of CRP and IL-6 is associated with type 2 diabetes, insulin resistance, and metabolic syndrome." (PMID 39683396, 2024). "Adipose tissue also produces pro-inflammatory cytokines, including tumour necrosis factor alpha (TNF-alpha) and interleukin-6 (IL-6), which promote inflammation and interfere with insulin signalling, leading to insulin resistance and increased risk of T2D14." (PMID 39406990, 2024). "It has been found that IL-6 causes impaired phosphorylation of the insulin receptor and insulin receptor substrate-1, leading to insulin resistance." (PMID 36979645, 2023). "The increased PBMCs’ mitochondrial OXPHOS capacity was associated with insulin resistance, systemic inflammation, and higher serum levels of interleukin-6 in the entire series of subjects." (PMID 36997629, 2023). "Chronic arsenic exposure increases TNF-α (at a concentration of 1 μM) and interleukin 6 (IL-6), which cause insulin resistance." (PMID 37396849, 2023). "The health of the adipose tissue and its role in driving inflammation and insulin resistance is associated with other markers, including IL-1, IL-6, and TNF-alpha." (PMID 37108980, 2023). "Outstandingly, increased circulating levels of inflammatory markers such as CRP and IL-6 have been linked to insulin resistance and progression to T2DM." (PMID 38004306, 2023). "IL-6 is a pleiotropic cytokine with respect to insulin resistance; while numerous studies have indicated its association with insulin resistance, others have reported its insulin-sensitizing effects." (PMID 37876013, 2023).
Insulin resistance (continued). "Proinflammatory IL-6 is a critical contributor to insulin resistance, and consequently has been implicated in the pathophysiology of T2D." (PMID 37892970, 2023). "IL-6 is a proinflammatory cytokine that conduces local and systemic inflammation, associated with clinical events of insulin resistance, cancer metastasis, and other inflammatory metabolic disorders." (PMID 37629569, 2023). "IL-6 causes a low-grade inflammation that affects insulin signaling and triggers insulin resistance." (PMID 37009872, 2023). "Tumour necrosis factor-α (TNF-α) and interleukin-6 (IL-6) are examples of proinflammatory cytokines that are known to cause insulin resistance by inhibiting insulin receptor signalling and hence raise the risk of T2DM." (PMID 37958258, 2023). "Insulin resistance can cause adipose tissue to secrete leptin, IL-6, TNF-α and other adipocytokines, and interact with these factors to cause the ‘second hit’, in which TNF-α plays a key role in this stage." (PMID 38041076, 2023). "In endothelial cells, IL-6 is implicated in ROS synthesis and NO production reduction, suggesting its contribution to the development of insulin resistance and atherosclerosis." (PMID 38136564, 2023). "TNF-α and IL-6, two main adipose-tissue-derived inflammatory cytokines, have been implicated in the induction of insulin resistance." (PMID 37893164, 2023). "Serum IL-6 levels were found to be associated with increased BMI, high fasting insulin levels, and insulin resistance in type 2diabetics." (PMID 38250529, 2023). "By contrast, in a chronic context, IL-6 is associated with insulin resistance and inflammation in skeletal muscle and liver." (PMID 36860845, 2023). "Several adipokine-associated molecules, such as tumor necrosis factor-alpha, interleukin-1β, and interleukin-6, have been linked to increased insulin resistance, inflammation, and fat accumulation." (PMID 37762592, 2023). "The recruitment of macrophages is the main characteristic of inflammation in white adipose tissue and promoted the secretion of TNF-α, IL-2, and IL-6 which cause insulin resistance." (PMID 36647430, 2023). "It has been proven that adipose tissue-resident macrophages lead to the release of TNF-α and IL-6, which are implicated in the induction of insulin resistance." (PMID 36353235, 2022). "Other authors have shown that increased production of SCFAs by gut microbiota is not only associated with reduced insulin resistance but also with reduced inflammatory markers including NF-ĸΒ and IL-6 in liver." (PMID 36553814, 2022). "The interleukin 6 (IL6)/JAK2/STAT3 signal transduction in the skeletal muscle of T2D patients plays a pathogenic role in the process of insulin resistance." (PMID 36555403, 2022). "Increased levels of TNF-α and IL-6, in addition to many other factors, are the cause of insulin resistance." (PMID 36362227, 2022). "Previous research has shown that excessive production of pro-inflammatory cytokines (TNF-α, IL-1β, IL-6) causes chronic inflammation and insulin resistance." (PMID 36056976, 2022). "Increased levels of proinflammatory cytokines such as TNF-α IL-1, and IL-6 have been shown to promote insulin resistance and cause metabolic disturbances in children with vitiligo." (PMID 37632859, 2022). "Increased levels of IL-6 in the serum are associated with insulin resistance, which promotes hyperglycemia by releasing glucose from hepatic glycogen reserves." (PMID 35959169, 2022). "HOMA-IR as an index of insulin resistance and LDL/HDL ratio as a risk ratio, and serum concentrations of FFA, TNF-alpha, and IL-6 as factors involved in insulin resistance, were measured in high-fat diet/STZ-induced type 2 diabetic (HFD/STZ-induced T2D) mice." (PMID 35145895, 2022). "Pro-inflammatory cytokines, such as TNF-α and IL-6, disrupt the insulin signaling pathway, and cause insulin resistance." (PMID 35745208, 2022).
Insulin resistance (continued). "Several studies have demonstrated that hepatocyte-specific deficiency of STAT3 can lead to insulin resistance and increased expression of gluconeogenic genes via the disruption of interleukin-6 (IL-6) signalling." (PMID 35896788, 2022). "The participation of mTOR in the SOSC3/STAT3 pathway, induced by IL-6, can intensify insulin resistance, causing the development of related pathological disorders, such as T2DM and GDM." (PMID 35052633, 2022). "HIF-2α+/– mice indeed display ATM accumulation, insulin resistance and susceptibility to adipose tissue inflammation (TNFα and IL-6) upon overnutrition." (PMID 34876704, 2022). "IL-6 is also an essential proinflammatory factor that induces liver injury, causes hepatocyte apoptosis, manufactures insulin resistance, and is involved in the development and progression of NAFLD." (PMID 35399623, 2022). "Although high basal concentrations of IL‐6 are regarded to be inflammatory and have been linked to insulin resistance, acute exercise‐induced IL‐6 that is produced by skeletal muscle can increase both insulin sensitivity and glucose uptake." (PMID 35238491, 2022). "Further, the VAI was associated with chronic inflammation and insulin resistance, due to increases in free fatty acids, interleukin-6, tumor necrosis factor-α, and decreased adiponectin production, related to VAT." (PMID 35811709, 2022). "Interleukin-6 (IL-6), a classic proinflammatory cytokine, plays a prominent role in the inflammatory response and is associated with insulin resistance and T2DM." (PMID 35840989, 2022). "These inflammatory markers, such as tumor necrosis factor alpha (TNF-a), interleukin 6 (IL-6), C-reactive protein, and leptin, influence insulin resistance and growth hormone and cause an imbalance in protein synthesis, and lead to poor physical capacity." (PMID 35875029, 2022). "Increased levels of circulating IL-6 are associated with predisposition to T2D, insulin resistance, and T2D-associated vascular complications." (PMID 36232386, 2022). "Tumor-derived inflammatory mediators, including IL-6 and TNFα have causal roles in tissue-specific insulin resistance, including liver, adipose tissue, and skeletal muscle." (PMID 35244142, 2022). "Systemic and tissue-specific inflammation has also been implicated as a mechanistic link between obesity and insulin resistance, with interleukin-6 and c-Jun N-terminal kinase (JNK) signaling as key mediators." (PMID 35244142, 2022). "The proposed mechanisms of causation include: insulin resistance; role of leptin in sympathetic activation; increased levels of inflammatory biomarkers such as IL-6; hypercoagulability; genetics." (PMID 36412616, 2022). "TNF-α is mostly expressed in adipose cells and is associated with insulin resistance, while highly expressed IL-6 causes cytotoxicity in pancreatic β cells." (PMID 36276816, 2022). "Relevant in this context is the role of both TNF-α and IL-6 that induce an altered expression of insulin receptors with consequent worsening of insulin resistance status and associated hyperglycemia." (PMID 36142799, 2022). "Other cytokines and mediators associated with insulin resistance include IL-6, TNF and adipokines involved in insulin-receptor signaling." (PMID 36555867, 2022). "TNF-α can activate IL-6, IL-8, and other cytokines, form an inflammatory cascade, induce liver inflammation, lead to insulin resistance (IR), and cause NASH." (PMID 36091584, 2022). "As increased TNF-α and IL-6 are associated with the pathogenesis of insulin resistance, biologic DMARDs (e.g., TNF inhibitors and tocilizumab) were expected to decrease DM risk by increasing insulin sensitivity." (PMID 35456202, 2022). "Since IL-6 affects hepatocytes and causes insulin resistance, it is possible that infection-induced inflammation results in insulin resistance." (PMID 34832512, 2021). "Il-6, the major inflammatory mediator was reported to be positively associated with adiposity and insulin resistance." (PMID 33905632, 2021).
Insulin resistance (continued). "In an open-label study in depressed patients with BD (N = 34) receiving pioglitazone (15–30 mg/day), higher baseline IL-6 was associated with a favourable antidepressant response and improvement in insulin resistance." (PMID 34440563, 2021). "In fact, the causes of T2DM are environmental or genetic factors, the genetic polymorphism of cytokines like IL-6 and 10 caused by up/down regulation of inflammatory cytokines to trigger insulin resistance." (PMID 33858419, 2021). "It was postulated that, elevated IL-6 level is associated with insulin resistance and the development of types 2 diabetes mellitus through its suppressive effect on glucose transporter-4 and insulin receptor substrate-1 expression." (PMID 33905632, 2021). "In vitro study shows that IL-6 causes insulin resistance at the cellular level in both primary hepatocytes and HepG2 cells." (PMID 34831450, 2021). "Studies have reported that short-term treatment with IL-6 improves insulin-induced glucose uptake in skeletal muscles, although sustained treatment with IL-6 causes glucose intolerance and insulin resistance." (PMID 34943061, 2021). "The levels of inflammatory markers, such as TNF-α and IL-6, which are the root causes of insulin resistance in type 2 diabetic patients with type 2 diabetes, were decreased in the CCL4 antibody injection group, compared with those in the IgG-treated DM group." (PMID 33968046, 2021). "Inflammation can also cause insulin resistance, and IL6 can stimulate aromatase activity and the conversion of androgens into estrogen within adipose tissue, which all contribute to the ideal conditions for tumor formation." (PMID 34359595, 2021). "For example, IL-6, a cytokine renowned for its pro-inflammatory role, is associated with central obesity, hypertension, and insulin resistance." (PMID 34631754, 2021). "Although the possible role of miRNA-122 in modulation of inflammatory cascades is well described, the exact mechanism through which miRNA-122 affects TNF-α and IL-6 levels consequently linked to insulin resistance in T2DM patients remains poorly understood." (PMID 34077450, 2021). "Adding to the depth of the IL-6 cascade signaling chain of events, elevations in IL-6 from contracting muscles have been noted to increase insulin sensitivity and possibly decrease ones risk of developing insulin resistance, the precursor for T2DM." (PMID 34179543, 2021). "IL-6 is responsible for insulin resistance and has been associated with hypertension and atherosclerosis in murine models while TNF-α is a mediator of atherosclerosis and heart failure." (PMID 34445526, 2021). "Persistently elevated IL-6 levels are associated with the development of insulin resistance and metabolic syndrome." (PMID 34067712, 2021). "Interleukin-6 (IL-6), a proinflammatory cytokine mainly associated with insulin resistance and type 2 diabetes, plays an interesting role in BAT activation." (PMID 33546400, 2021). "Insulin resistance has also been associated with elevated levels of proinflammatory cytokines (Il-1, Il-6, TNF-α)." (PMID 34069618, 2021). "IL-6 was associated with the development of insulin resistance as well, and visceral adipose tissue is considered an important source of its production." (PMID 34869524, 2021). "Accumulating evidence indicates that IL-6 is involved in oxidative stress and inflammation in adipose, skeletal muscles, and hepatic tissues in association with insulin resistance and impaired fasting glucose." (PMID 34943061, 2021). "Nuclear factor-kB (NF-kB), which is linked to inflammation and insulin resistance, modulates several cytokines, including interleukin-6 (IL-6)." (PMID 34069890, 2021). "Insulin resistance is associated with elevated levels of proinflammatory cytokines such as C-reactive protein and IL-6, which are linked to Aβ deposition in the brain." (PMID 33597002, 2021). "Increased IL-6 production and prolonged elevated levels have also been linked to insulin resistance." (PMID 35008824, 2021).
Insulin resistance (continued). "Another detrimental factor in obese individuals include that adipose tissue produces inflammatory cytokines like TNF-α and interleukin-6 (IL-6), and these are known to induce insulin resistance as well as to cause aldosterone secretion." (PMID 34268323, 2021). "Current research shows that greater “body adiposity”, “scenarios of insulin resistance”, and “sarcopenia” are associated with increased systemic levels of various inflammatory markers (particularly IL-6 and TNFα)." (PMID 35010928, 2021). "Interleukin-6 (IL-6) is a pro-inflammatory cytokine that mediates inflammation associated with insulin resistance in the liver and other tissues." (PMID 33477364, 2021). "In short, various studies have proven that IL-6 can induce insulin resistance, and as a consequence indirectly exacerbates muscle loss in CAC." (PMID 34863141, 2021). "Conversely, chronic inflammation during RA is associated with persistent elevations of IL6 and insulin resistance and with an increased risk of metabolic syndrome even in patients of normal weight." (PMID 33573047, 2021). "At the beginning of the 21st century, the increased secretion of cytokines, especially TNF-α and IL-6, which contribute to insulin resistance, was proved to be linked to infiltration and accumulation of macrophages in adipose tissue." (PMID 32947869, 2020). "Pro-inflammatory M1-macrophages are key factors in generating inflammatory molecules, such as TNFα, IL-1ß and IL-6, that cause insulin resistance both in adipose tissue and other insulin-sensitive tissues." (PMID 32183037, 2020). "We also documented a significant increase in IL-6 concentrations following baricitinib administration, consistent with a previous study showing that IL6-deficient mice fed HD develop significant hepatosteatosis and insulin resistance." (PMID 32413585, 2020). "It was also found that “Inactive & Sedentary LS”, high BF%, insulin resistance, and ultra-sensitive C-reactive protein were associated with the concentrations of proinflammatory biomarkers of tumor necrosis factor-α, interleukin-6, and leptin." (PMID 32694929, 2020). "Adipokines generated by visceral fat pads, such as IL-6, are thought to influence growth hormone secretion and insulin resistance, which are strongly associated with muscle atrophy." (PMID 32049987, 2020). "Metformin therapy reduces plasma levels of interleukin-6 (IL-6), an inflammatory cytokine associated with insulin resistance and diabetes risk." (PMID 32754618, 2020). "The secreted cytokines TNFα and IL-6 cause insulin resistance in adipocytes through IKKβ and JNK1 kinase pathway activation, which interfere with insulin signaling via phosphorylation and subsequent IRS1 inactivation." (PMID 32878255, 2020). "Studies have confirmed that IL-6 and its expression are associated with insulin resistance and β-cell dysfunction, diabetic retinopathy and obstructive sleep apnea hypopnea syndrome (OSAHS) in T2DM." (PMID 33016995, 2020). "IL-6 is associated with insulin resistance and hyperandrogenism, and it is regarded as an early low-grade chronic inflammatory marker in PCOS patients." (PMID 31399035, 2019). "The expression of various pro-inflammatory cytokines such as TNF-α and IL-6 is increased in adipose tissue and its expression linked to systemic inflammation and accompanying insulin resistance in patients T2DM." (PMID 31554278, 2019). "Increased plasma levels of TNFα and IL6 are associated with insulin resistance (Shoelson, Herrero, & Naaz, 2007), inconsistent to observations made here where HFD‐fed Park2 KO mice were more insulin sensitive despite increased plasma TNFα and IL6 levels." (PMID 31724300, 2019). "After a 2-y follow-up, the Mediterranean diet was associated with decreased hsCRP, IL-6, and insulin resistance in patients with metabolic syndrome; and associated with increased adiponectin and decreased CRP in T2D patients." (PMID 30927000, 2019).